RIPK1 (receptor interacting serine/threonine kinase 1)
Diseases named in the same sentence as RIPK1 in open-access papers (continued):
Sharing a sentence is not in itself a finding about the gene and the disease.
fibrosarcoma (3 papers, 2020 to 2022). A malignant mesenchymal fibroblastic neoplasm affecting the soft tissue and bone. "Here we report that A179L enhanced TNF-α or TSZ (TNF-α, Smac, and Z-Vad)-induced receptor-interacting protein kinase (RIPK1), RIPK3, and mixed lineage kinase domain like peudokinase (MLKL) phosphorylation in L929 cells, a murine fibrosarcoma cell line." (PMID 34960759, 2021). "Treatment with TNF resulted in the formation of the TNF receptor signalling complex‐I (TNFR‐SC, also referred to as complex‐I) in the human fibrosarcoma cell line HT1080, as evidenced by the recruitment of bona fide TNFR‐SC components such as RIPK1, SHARPIN and TRADD (Fig EV2A)." (PMID 32419365, 2020).
Hyperglycemia (3 papers, 2022 to 2024). An increased concentration of glucose in the blood. "Primary cultured renal tubular epithelial cells demonstrated that hyperglycemia was associated with increased levels of phospho-RIPK1 at S161 and S166." (PMID 37928264, 2023). "Notably, hyperglycemia-associated elevations in phospho-RIPK1 levels were augmented by PINK1 deficiency." (PMID 37928264, 2023). "Interestingly, we observed that hyperglycemia-treated and/or PINK1-deficient HKC-8 cells exhibited increased levels of phospho-RIPK1 at S161 and S166, respectively, both of which were involved in necroptosis initiation 26,48." (PMID 37928264, 2023). "Thus, the RIPK1/RIPK3 pathway is a promising target for alleviating MF induced by hyperglycemia." (PMID 35165268, 2022).
myocardial hypertrophy (3 papers, 2016 to 2023). "Knockdown of RIPK1 or RIPK3 by siRNA suppressed the PA-induced myocardial hypertrophy." (PMID 27057269, 2016). "In mice with cardiac hypertrophy, the expression of RIPK3 downstream protein RIPK1 and the phosphorylation of MLKL were inhibited, and meanwhile, apoptosis was improved." (PMID 37833985, 2023). "Overexpression of RIPK3 simultaneously up-regulated the expression of RIPK1 and the phosphorylation of MLKL in the myocardial tissues of mice with cardiac hypertrophy." (PMID 37833985, 2023). "Western blotting analysis showed that the expressions of RIPK1 and phosphorylated MLKL in the myocardium of RIPK3−/− mice with myocardial hypertrophy were significantly lower compared with WT mice." (PMID 37833985, 2023). "Our results showed that the expression of RIPK1 and the phosphorylation of MLKL were significantly up-regulated in the myocardium of WT mice with myocardial hypertrophy, and the levels of serum IL-6 and TNF-α were increased." (PMID 37833985, 2023). "The results of the present study revealed that expression of RIPK1 and phosphorylation of MLKL were significantly upregulated in the myocardium of WT myocardial hypertrophy mice, and the levels of serum IL-6 and TNF-α were increased." (PMID 36046685, 2022).
pancreatic adenocarcinoma (3 papers, 2020 to 2025). "The overexpression of RIPK1 was also detected in pancreatic adenocarcinoma cells and increased after chemotherapy." (PMID 40508046, 2025). "The expression of RIPK1, RIPK3, and MLKL was also reported to be upregulated in pancreatic adenocarcinoma (PDA)." (PMID 31914150, 2020).
pneumonia (3 papers, 2018 to 2025). An acute, acute and chronic, or chronic inflammation focally or diffusely affecting the lung parenchyma, caused by an infection in one or both of the lungs (by bacteria, viruses, fungi, or mycoplasma.). "The KPn pneumonia model further corroborates that targeting the necroptosis pathway (via RIPK1/RIPK3 inhibitors) not only restores efferocytic capacity but also significantly improves disease outcomes." (PMID 40861493, 2025). "Moreover, blocking agrA and psmα expression significantly suppressed the neutrophil necroptosis induced by S. aureus and effectively prevented pneumonia through the psmα mutant strain, with RIP as agr inhibitor and Nec as RIPK1 inhibitor." (PMID 29500427, 2018).
primary immunodeficiency (3 papers, 2021 to 2025). "Although patients with RIPK1 deficiency develop primary immunodeficiency associated with peripheral T cell lymphopenia, the impact of this deficiency on intestinal T cells remains unexplored." (PMID 40307618, 2025).
Salmonella Infections (3 papers, 2020 to 2024). Infections with bacteria of the genus SALMONELLA. "The KEGG pathway analysis identified two significant pathways, namely Salmonella infection and intercellular junction, involving the RIPK1 and TUBB2B genes." (PMID 39682314, 2024). "To determine whether RIPK1 is involved in SpvB-mediated necroptosis, we measured phospho-RIPK1 (p-RIPK1) level in Caco-2 cells after Salmonella infection." (PMID 35110556, 2022). "In this study, we show that TRADD, FADD, and RIPK1 are GlcNAcylated by NleB, TRADD is GlcNAcylated by SseK1, and TNFR1 is GlcNAcylated by SseK3 during EPEC or Salmonella infection, which are consistent with previous studies." (PMID 32432056, 2020).
type 2 diabetes (3 papers, 2022 to 2024). "We used db/db mice as a model for type 2 diabetes to investigate whether receptor‐interacting serine/threonine protein kinase 1 (RIPK1), which is expressed in microglia in the hippocampal region, is a key protein partner for RAGE." (PMID 37665158, 2024).
Acute hepatitis (2 papers, 2016 to 2022). Acute hepatic injury resulting from inflammation typically accompanied by increased serum alanine transaminase activity. "In order to explore the pro-survival role of RIPK1 in the ConA-induced acute-hepatitis model, we used the Ripk1LPC-KO mice that are fully deficient for both RIPK1 scaffold and kinase functions." (PMID 27831558, 2016). "Thus, some works demonstrated the protective role of RIPK1 in hepatocytes during different acute hepatitis involving TNF-α." (PMID 35806372, 2022). "Besides, RIPK1 is known to play a protective role in different type of acute hepatitis involving TNF-α." (PMID 35806372, 2022). "Therefore, the involvement of RIPK1 in CCl4-induced acute hepatitis engages its platform function but not its kinase activity." (PMID 35806372, 2022). "Thus, during CCl4 acute hepatitis, FasL appeared to participate to the protection of hepatocytes when these cells are not modified and expressed RIPK1, while its absence in liver parenchymal cells sensitize them to the pro-death function of FasL." (PMID 35806372, 2022). "Thus, we demonstrated that RIPK1 depletion specifically in liver parenchymal cells sensitizes mice (Ripk1LPC-KO) to CCl4-induced hepatocyte apoptosis, while genetic inactivation of its kinase activity (Ripk1K45A) never affected CCl4-induced acute hepatitis." (PMID 35806372, 2022).
acute liver failure (2 papers, 2019 to 2022). Rapid deterioration of liver function causing encephalopathy and coagulopathy. "Poly I:C-treated animals with RIPK1-deficient hepatocytes developed the usual symptoms of acute liver failure accompanied by an enhanced systemic release of TNF-α, which was responsible for hepatocyte death." (PMID 30622241, 2019).
anemia (2 papers, 2022 to 2024). A reduction in the number of red blood cells, the amount of hemoglobin, and/or the volume of packed red blood cells. "Since SENP1 deficiency in mice leads to embryonic lethality due to massive fetal liver apoptosis and anemia after post-coital day E14.527, we considered the possibility that RIPK1 activation might contribute to the cell death phenotype of SENP1-deficient mice." (PMID 36414671, 2022). "Thus, RIPK1 kinase-dead knockin mutation does not rescue the embryonic lethality of Senp1−/− mice probably due to the failure in preventing anemia caused by erythropoiesis defects and blood vessel development defects." (PMID 36414671, 2022).
Anxiety (2 papers, 2023). Intense feelings of nervousness, tension, or panic often arise in response to interpersonal stresses. "Behavioral tests indicated that inhibition of RIPK1 greatly relieved motor dysfunction and anxiety-like behaviors of PD mice." (PMID 37239205, 2023).
astrocytoma (2 papers, 2021 to 2025). "In fact, significant upregulations of MYD88, SRF, JUN, IL1B, TRIF, RIPK1, NLRP3 were detected in GBM cases compared to lower grade astrocytomas (AGII and AGIII)." (PMID 33446690, 2021). "Our transcriptomic data of U87MG cells 12 h after LPS stimulation and the TCGA RNASeq dataset of astrocytoma showed upregulation of genes related to inflammasome and ripoptosome pathways, namely MYD88, NLRP3, RIPK1 and RIPK3, and also SRF, JUN and IL1B, the downstream regulated genes." (PMID 33446690, 2021).
autoimmune lymphoproliferative syndrome (2 papers, 2022 to 2023). Autoimmune lymphoproliferative syndrome (ALPS) is a rare, inherited disorder characterized by non-malignant lymphoproliferation, multilineage cytopenias, and a lifelong increased risk of Hodgkin's and non-Hodgkin's lymphoma. "Though Mlkl−/−Fadd−/− or Ripk3−/−caspase-8−/− mice are able to fully rescue Ripk1D325A/D325A animals, there were characteristic autoimmune lymphoproliferative syndrome (ALPS) observed in the surviving mice, suggesting the role of activated RIPK1 in mediating inflammation independent of necroptosis." (PMID 36969188, 2023).
brain tumor (2 papers, 2019 to 2020). "The overexpression of RIPK1 was associated with a poor prognosis for brain tumors based on altering the apoptosis." (PMID 32272907, 2020). "The PERK inhibitor GSK2606414 blocks brain tumor cell migration, but this inhibitor is also known to target RIPK1 and c-KIT." (PMID 31064137, 2019).
Caroli disease (2 papers, 2021). Caroli disease (CD) is a rare congenital liver disease characterized by non-obstructive cystic dilatations of the intra-hepatic and rarely extra-hepatic bile ducts. "RIPK1 was consistently detectable in biliary epithelial cells of cystically dilated bile ducts of patients with Caroli disease/syndrome (with additional congenital hepatic fibrosis)." (PMID 33798093, 2021).
cerebral infarction (2 papers, 2020 to 2024). An ischemic condition of the brain, producing a persistent focal neurological deficit in the area of distribution of the cerebral arteries. "The pairwise comparison showed that those with different cerebral infarction volumes all had a much higher content of serum RIPK1, RIPK3, and TNF‐α than the control (p < 0.05)." (PMID 39657719, 2024). "Intracerebroventricular injections of Nec‐1 (a specific inhibitor of RIPK1) can prematurely reduce the volume of cerebral infarction more effectively compared with the therapeutic effects noted by the inhibition of apoptosis." (PMID 32990414, 2020). "This evidence implied that treatment with targeted inhibition of RIPK1 could widen the time window of treatment in the acute phase of cerebral infarction." (PMID 32990414, 2020). "Comparison of serum RIPK1, RIPK3, and TNF‐α levels in patients with different volumes of cerebral infarction." (PMID 39657719, 2024). "Serum RIPK1, RIPK3, and TNF‐α levels between the control group and different cerebral infarction volume groups were compared using ANOVA." (PMID 39657719, 2024). "AIS patients in ICU had abnormally elevated content of serum RIPK1 and RIPK3, which was closely related to the volume of cerebral infarction, severity and the prognosis." (PMID 39657719, 2024). "The content of serum RIPK1 and RIPK3 was gradually elevated with increased cerebral infarction volume and the severity of the disease (p < 0.05)." (PMID 39657719, 2024). "In general, AIS patients in the ICU had abnormally elevated content of serum RIPK1 and RIPK3, which were closely related to the volume of cerebral infarction, severity, and prognosis." (PMID 39657719, 2024). "In this study, the correlation between RIPK1 and RIPK3 with cerebral infarction volume, severity, and prognosis in AIS patients was explored, aiming to provide new targets for the treatment of AIS and bring better prognosis to patients." (PMID 39657719, 2024). "AIS patients in the ICU had abnormally elevated content of serum RIPK1 and RIPK3, which was closely related to the volume of cerebral infarction, severity, and prognosis." (PMID 39657719, 2024).
chronic kidney disease (2 papers, 2022 to 2025). Impairment of the renal function secondary to chronic kidney damage persisting for three or more months. "The molecular mechanisms by which RIPK1 and RIPK3 contribute to kidney fibrosis during the transition from AKI to chronic kidney disease are the subject of ongoing investigation." (PMID 39705008, 2025). "Our data do not establish whether transiently inhibiting RIPK1 or RIPK3 early during the AKI to chronic kidney disease transition reduced the severity of fibrosis or merely delayed its onset." (PMID 39705008, 2025).
chronic liver failure (2 papers, 2021 to 2023). Liver failure that develops slowly and gradually for some time, possibly for years, often as the result of cirrhosis, or malnutrition. "In the mouse model of acute on chronic liver failure, using LPS to stimulate chronic liver failure mice, it was found that RIPK1-mediated cell death in liver cells could be induced, and the use of NEC-1 could alleviate the degree of acute liver failure." (PMID 37090690, 2023).
Cirrhosis (2 papers, 2021 to 2025). A chronic disorder of the liver in which liver tissue becomes scarred and is partially replaced by regenerative nodules and fibrotic tissue resulting in loss of liver function. "In addition to inhibiting RIPK1 and RIPK3, inhibition of the TLR4 pathway by TAK-242 or TLR4 deficiency was found to significantly reduce circulating ammonia levels, which was validated in clinically relevant models of hyperammonemia due to cirrhosis or UCD." (PMID 40053595, 2025). "RIPK3 plasma levels and hepatic expression of RIPK1, RIPK3, and pMLKL were measured in healthy volunteers, stable patients with cirrhosis, and in hospitalized cirrhotic patients with acutely decompensated cirrhosis, with and without ACLF (AD)." (PMID 34921136, 2021).
colorectal adenocarcinoma (2 papers, 2018 to 2022). The most common type of colorectal carcinoma. "In two human colorectal adenocarcinoma lines, HT-29 and COLO 205, that are sensitive to necroptosis induced by treatment with TNFα, zVAD-fmk, and cIAP inhibitor BV6, multiple sgRNAs targeting PTBP1 enhance inclusion of the RIPK1 alternative exon." (PMID 29449584, 2018).
dilated cardiomyopathy (2 papers, 2022 to 2025). Cardiomyopathy which is characterized by dilation and contractile dysfunction of the left and right ventricles. "Here, we identified a key disease mechanism for TAB2 deficiency–induced dilated cardiomyopathy, which involves aberrant RIPK1 activation and the induction of RIPK1-dependent apoptosis and necroptosis." (PMID 34990405, 2022). "Our results also suggest that targeting RIPK1-mediated cell death signaling may represent a promising therapeutic strategy for TAB2 deficiency–induced dilated cardiomyopathy." (PMID 34990405, 2022). "Research has proven that RIPK1 activation exacerbated diabetic cardiac injury and dilated cardiomyopathy." (PMID 40822127, 2025). "Taken together, these data reveal a key role for RIPK1-dependent apoptosis and necroptosis in the pathogenesis of TAB2 deficiency–induced dilated cardiomyopathy." (PMID 34990405, 2022).
Fulminant hepatitis (2 papers, 2016 to 2019). Acute hepatitis complicated by acute liver failure with hepatic encephalopathy occurring less than 8 weeks after the onset of jaundice. "Although the host defense system is insufficient to protect C57BL/6 mice from fatal MHV3 fulminant hepatitis, RIPK1 appeared to partly contribute to some resistance underlying the protective function played by RIPK1 in hepatocytes." (PMID 30622241, 2019). "Our data demonstrated that, contrary to WT littermates, ConA injection resulted in a fulminant hepatitis in Ripk1LPC-KO mice, in part caused by the sensitization of RIPK1-deficient liver parenchymal cells to apoptosis." (PMID 27831558, 2016). "Our investigations demonstrated that RIPK1 protects hepatocytes from TNF-α secreted from macrophages during viral induced fulminant hepatitis." (PMID 30622241, 2019).
fungal infection (2 papers, 2020 to 2023). "The residual activation we observed in ZBP1/RIPK3-deficient BMDMs in this study suggests that there could be additional pathways or PANoptosome components such as RIPK1 that are functioning during fungal infection." (PMID 33109609, 2020).
Gaucher disease (2 papers, 2021 to 2022). Gaucher disease (GD) is a lysosomal storage disorder encompassing three main forms (types 1, 2 and 3), a fetal form and a variant with cardiac involvement (Gaucher disease - ophthalmoplegia - cardiovascular calcification or Gaucher-like disease). "Increased abundance of Ripk1 was also detected in a human Gaucher disease brain." (PMID 34172992, 2021). "It is also known that RIPK1 and RIPK3 expression levels are increased in the brains of mice with Gaucher disease and Niemann-Pick disease." (PMID 36778591, 2022).
glaucoma (2 papers, 2025 to 2026). Increased pressure in the eyeball due to obstruction of the outflow of aqueous humor. "Also, RIPK1/RIPK3 inhibition or RIPK1/3 gene manipulation can prevent RGC loss in several models of glaucoma, such as ischemia/reperfusion, optic nerve crush, and glutamate excitotoxicity." (PMID 40345829, 2025). "TNF is a potent inflammatory agent in the pathology of glaucoma, and TNF-related necroptosis is promoted by the RIPK1/RIPK3 axis." (PMID 40345829, 2025).
infarct (2 papers, 2021 to 2023). "Furthermore, Hsp70.1B knockdown exacerbated infarction volume and behavioral deficits, decreased lysosomal membrane integrity and blocked RIPK1 inhibitor necrostatin-1-mediated protection of lysosomal membranes." (PMID 37055533, 2023).
inflammatory skin disease (2 papers, 2021 to 2023). Inflammatory skin disorders covers a broad category that includes many conditions ranging in severity, from mild itching to grave medical health complications These disorders are common in people of all ages and races. "This argues for therapeutic testing of RIPK1 or RIPK3 inhibitors in certain skin inflammatory diseases." (PMID 37688617, 2023).
intestinal tumors (2 papers, 2022). "In COAD, RIPK3-mediated inflammation can promote intestinal tumors by inducing an immune-suppressive tumor microenvironment, and RIPK1 has been shown to interact with mitochondrial Ca2+ uniporter to promote colorectal oncogenesis." (PMID 36505813, 2022).
ischemic heart disease (2 papers, 2022 to 2024). "Therefore, the FTO/circCacna1c/Hnrnpf/RIPK1 axis holds great potential as an effective target for attenuating cardiac injury caused by necroptosis in ischemic heart disease." (PMID 39533214, 2024). "Thus, functional interaction between MG53 and RIPK1 might be a potential target for treating ischemic heart diseases." (PMID 35711363, 2022).
kidney injury (2 papers, 2016 to 2023). Trauma to the kidney. "exhibited that wogonin alleviates cisplatin-triggered acute kidney injury via repressing RIPK1-mediated necroptosis." (PMID 36866869, 2023).